RND3 (Rho family GTPase 3)
Diseases named in the same sentence as RND3 in open-access papers (continued):
Sharing a sentence is not in itself a finding about the gene and the disease.
glioma (11 papers, 2013 to 2023). A benign or malignant brain and spinal cord tumor that arises from glial cells (astrocytes, oligodendrocytes, ependymal cells). "The result indicates that Notch activation is responsible for RND3 deficiency-induced glioma cell proliferation." (PMID 26108681, 2015). "In GBMs, Rnd3 is upregulated when compared to low-grade gliomas, although its impact on cell migration and invasion is still unclear owing to contradictory data." (PMID 36496976, 2022). "Secondly, our models have highlighted that low and high-grade gliomas are characterised by a switch in the activity of two different sets of Rho GTPases, among which RND3 is a key regulator of tumour proliferation, migration, apoptosis and invasion." (PMID 26132659, 2015). "RND3 protein was significantly up-regulated in grade IV gliomas compared to both grade II and grade III." (PMID 26132659, 2015). "Downregulation of RND3, however, enhanced Notch signaling activity, and subsequently promoted glioma cell proliferation." (PMID 26108681, 2015). "In this study, we at least provided a partial answer to the question as we identified RND3 as an endogenous inhibitor of Notch in gliomas." (PMID 26108681, 2015). "Overexpression of RND3 diminishes Notch signaling, which in turn inhibits glioma cell proliferation and tumor growth in xenograft mice." (PMID 26108681, 2015). "To determine the clinical significance of RND3 in gliomas, we assessed and compared the expression levels of RND3 transcript and protein in human GBM specimens, the glioma adjacent brain areas (tissues) (ABT, 3 cm away from glioma), and normal brain tissues." (PMID 26108681, 2015). "Further characterisation of a high-grade glioma transcriptional network highlights a pivotal role of the Rho GTPase RND3 (also known as RhoE, Entrez: 390) in controlling tumour proliferation, migration and invasion." (PMID 26132659, 2015). "We tested the expression of RND3 which on the basis of the numbers of inferred network connections we predicted to have differential activity across glioma grades." (PMID 26132659, 2015). "Next, the development and application of a novel data integration methodology reveals novel functions of RND3 in controlling glioma cell migration, invasion, proliferation, angiogenesis and clinical outcome." (PMID 26132659, 2015). "LncRNA HOXA-AS2 regulated malignant glioma behaviors via the RND3 expression and miR-373/EGFR axis." (PMID 33178271, 2020). "Three genes closely related to glioma, RND3, OSMR, and CREB3L2, were significantly upregulated and might be the key factors in EBLN1 regulating the proliferation and apoptosis of OL cells." (PMID 27023521, 2016). "Network analysis revealed RND3 as the most connected factor for high-grade glioma." (PMID 26132659, 2015). "Firstly, the expression of RND3 was determined in several cell lines from different glioma grades." (PMID 26132659, 2015). "This interaction may participate, in addition to its known modulatory activity on RhoA activity, to the biological effects triggered by RND3 in glioma cells." (PMID 26132659, 2015). "In addition, a previous study in glioma positioned RND3 as an anti-tumour gene, decreasing proliferation and inducing apoptosis in U87 cells." (PMID 26132659, 2015). "Downregulation of RND3 enhances Notch signaling activity, promoting glioma cell proliferation." (PMID 26108681, 2015). "RND3 and other Rho GTPases are transcriptionally regulated in high-grade glioma." (PMID 26132659, 2015). "Both data strongly suggest that RND3 negatively regulates Notch signaling in human glioma cells." (PMID 26108681, 2015). "In glioma cells, HOXA-AS2 recruits EZH2 to upregulate RND3 and promote the proliferation of glioma cells, thereby accelerating tumor growth." (PMID 33430870, 2021).
glioma (continued). "To determine the clinical significance of RND3 in gliomas, we assessed and compared the expression levels of RND3 transcript and protein in human GBM specimens, the normal brain tissues (NB) (glioma adjacent brain areas, 3 cm away from glioma)." (PMID 27705942, 2016). "To further verify the downregulation of RND3 expression in GBM, we compared the expression levels of RND3 protein and transcript in four pairs of patient-matched GBM specimens and the corresponding glioma ABTs." (PMID 26108681, 2015). "We confirmed the difference in RND3 expression in tumour cells by immunohistochemistry analysis of grade II, III and IV gliomas." (PMID 26132659, 2015). "This includes effects on cell invasion (RAC1, RAC2, RAC3, RHOA, RHOC), focal adhesion formation (RHOA), stemness of glioma precursor cells (RAC1), cell proliferation (RAC1, RND3) and cell cycle (RND3)." (PMID 26132659, 2015). "However, the expression of RND3 protein in different glioma grades is unknown." (PMID 26132659, 2015). "Seven Rho GTPases (RND1, RND3, RAC3, RHOA, RAC2, RAC1 and RHOC) showed a significantly greater connectivity in grade IV glioma and seven (CHP, RHOD, RHOF, RHOB, RHOQ, RND2, RHOBTB3) showed greater connectivity in grade II glioma." (PMID 26132659, 2015). "Three genes RND3, OSRM, and CREB3L2 were focused, for their closely relation to glioma." (PMID 27023521, 2016). "In this study, we confirmed the inhibitory regulation of RND3 on Notch in glioma cells, and quantified the negative effects of RND3 on Notch activity by multiple quantitative ChIP assays." (PMID 26108681, 2015).
breast carcinoma (7 papers, 2010 to 2024). "Meanwhile, UXT is highly expressed in breast cancer and that UXT suppresses RND3 epigenetically by recruiting EZH2 in breast cancer." (PMID 37152054, 2023).
lung cancer (6 papers, 2014 to 2026). A malignant neoplasm involving the lung. "The analysis of Rnd3 levels in human lung specimens from the TCGA database and K-M plot revealed the association between enhanced Rnd3 expression and lung cancers." (PMID 27144337, 2016). "Increased Rnd3 expression levels in lung cancers tissues have been identified by a genome database TCGA, and have been linked to less overall survival probabilities of lung cancer patients." (PMID 27144337, 2016). "Rnd3 mRNA expression in 110 paired human lung cancer specimens and normal tissues were retrieved from the TCGA database." (PMID 27144337, 2016). "The OS for patients with high Rnd3 expression was lower than that of those with low Rnd3 expression, suggesting that Rnd3 was a prognostic indicator for OS of patients with lung cancers." (PMID 27144337, 2016). "Overexpression of Rnd3 might serve as an unfavorable prognostic factor in lung cancer patients." (PMID 27144337, 2016). "However, the role of Rnd3 in lung cancers, specifically in NSCLC, remains unclear." (PMID 25372032, 2014). "Given the fact that Rnd3 was down-regulated in NSCLC cells and down-regulation of Rnd3 promoted the NSCLC cells proliferation, it would be interesting and necessary to evaluate the Rnd3 expression in human lung cancer tissue specimens." (PMID 25372032, 2014). "The biological role of activation of these two signaling pathways in NSCLC, and the relationship between Rnd3 down-regulation and NICD up-regulation in lung cancers has not yet been characterized." (PMID 25372032, 2014).
prostate carcinoma (6 papers, 2010 to 2022). A carcinoma that arises from epithelial cells of the prostate gland. "Up-regulation of the small G-protein RhoE/Rnd3/Rho8 inhibits the proliferation of prostate cancer cells by promoting apoptosis and inhibiting cell cycle progression." (PMID 22347457, 2012). "RND3 is under-expressed in prostate cancer and induces apoptosis and cell cycle arrest." (PMID 26132659, 2015). "However, evidences strongly support Rnd3 may act as an anti-oncogene, such as hepatocellular carcinoma, squamous cell carcinoma, breast cancer, prostate cancer, colorectal carcinoma, and lung cancer." (PMID 28881704, 2017). "In prostate cancer cells, Rnd3 expression induces the cells arrested in G2/M rather than in G1, as seen in fibroblasts, suggesting that Rnd3 has the ability to regulate cell cycle progression at different phases." (PMID 25372032, 2014).
squamous cell carcinoma (6 papers, 2014 to 2024). A carcinoma arising from squamous epithelial cells. "Previous results have shown that, in squamous cell carcinomas, RND3 was essential for the recruitment of intracellular domain of NOTCH1 to its target gene promoters by favoring NOTCH1 translocation to the nucleus." (PMID 38343633, 2024). "For example, in squamous cell carcinoma RND3 seems to mediate the translocation of the intracellular domain of NOTCH1 to the nucleus and its binding to the promoter of its target genes." (PMID 38343633, 2024). "Our results agree with those observed in squamous cell carcinomas, where RND3 depletion suppresses NOTCH1-mediated signaling." (PMID 38343633, 2024). "A recently published study highlighted that Rnd3 was a downstream mediator of Notch signaling in squamous cell carcinomas (SCC) in skin epithelia." (PMID 25372032, 2014).
colorectal cancer (5 papers, 2013 to 2024). A primary or metastatic malignant neoplasm that affects the colon or rectum. "For example, in colorectal cancer, miR-200b is transferred between adjacent cancer cells, where it directly targets 3′-UTRs of p27 and Rho Family GTPase 3 (RND3), two proteins involved in cell cycle regulation, leading to their downregulation, which in turn induces proliferation in recipient cells." (PMID 35884411, 2022). "Rnd3 was up-regulated in colorectal cancer compared to normal human colorectal tissue." (PMID 25372032, 2014).
non-small cell lung carcinoma (5 papers, 2014 to 2022). A group of at least three distinct histological types of lung cancer, including non-small cell squamous cell carcinoma, adenocarcinoma, and large cell carcinoma. "miR-200b/-c targeted rho family GTPase 3 (RhoE) and inhibited the proliferation of non-small cell lung cancer cells." (PMID 35682560, 2022). "In the non-small cell lung cancer tissues, the expression of Rnd3, mRNA, and protein levels were dramatically increased, compared to that of adjacent non-tumoral lung tissues." (PMID 27144337, 2016). "The expression of Rnd3 and its ectopic role in non-small cell lung cancer (NSCLC) remain to be explored." (PMID 25372032, 2014).
Obesity (5 papers, 2021). Accumulation of substantial excess body fat. "Although the precise roles remain uncertain, previous studies have revealed that Rnd3 also mediates obesity and insulin resistance." (PMID 34306321, 2021).
Diabetes (4 papers, 2012 to 2025). "In contrast, Rnd3 expression deficiency accentuated fibrosis and cardiac dysfunction in diabetes." (PMID 36438502, 2022). "Diabetes and high glucose (HG, 35 mmol/L D-glucose) suppressed Rnd3 expression in cardiomyocytes and induced cardiomyocyte senescence." (PMID 40025898, 2025). "While db/db, ob/ob, HFD/STZ, and HFD models 14, 44 are commonly used as T2DM mouse models, the critical role of Rnd3 in DCM should be validated in human diabetes and other murine models of diabetes." (PMID 36438502, 2022). "Rnd3 overexpression reduced the reactive oxygen species (ROS) generation, a cardinal mediator of fibrosis in diabetes mellitus 25, in fibroblasts." (PMID 36438502, 2022). "In this context, Rnd3 plays an undisputedly key role in the heart, although its role in ventricular remodeling remains unclear in diabetes." (PMID 36438502, 2022). "Type 2 diabetes mellitus was established in Rnd3 fibroblast-specific knockout and transgenic mice." (PMID 36438502, 2022). "Remarkably, ∼50% of these protein-coding genes were also DE following anti-diabetes drug-treatment; including ALDH6A DHTKD1, PCYT2 and RND3 (this compares with <5% of the transcriptome responding to drug -treatment)." (PMID 29986096, 2018).
endometriosis (4 papers, 2014 to 2022). The growth of functional endometrial tissue in anatomic sites outside the uterine body. "This work has shown EZH2 and RND3 to have a high value in diagnosing endometriosis and being effective diagnostic biomarkers." (PMID 34790699, 2021). "The expression levels of EZH2 (Enhancer of Zeste homolog 2) and RND3 (also known as RhoE) had statistically significant changes with higher values in the endometriosis group compared with the controls, both in the tissue samples and primary ESCs." (PMID 34790699, 2021). "Spearman correlation analysis depicted that the relative expression levels of EZH2 and RND3 were positively correlated with CA125 of the corresponding endometriosis samples, (r = 0.7817, p < 0.0001) and (r = 0.7793, p < 0.0001), respectively." (PMID 34790699, 2021). "Next, we calculated the diagnostic value of the 12 hub ATGs for endometriosis using the ROC analysis, and the results showed the high sensitivity and specificity of EZH2 (AUC: 99.0%) and RND3 (AUC: 94.0%) in diagnosing endometriosis." (PMID 34790699, 2021). "Among them, the differences in the expression levels of EZH2, IQCG, and RND3 between the endometriosis group and control group were the most statistically significant (p < 0.001)." (PMID 34790699, 2021). "Rs6734792 on 2q23.3, P = 2.2 × 10−6 with all-stage endometriosis, is located 280 kb upstream of RND3 (Rho Family GTPase 3)." (PMID 24676469, 2014). "In view of above results, protein expression of EZH2, RND3, and IQCG were subsequently measured in endometriosis cells and tissues by Western blotting, which demonstrated similar results to those of the mRNA level." (PMID 34790699, 2021).
Hydrocephalus (4 papers, 2015 to 2024). Hydrocephalus is an active distension of the ventricular system of the brain resulting from inadequate passage of CSF from its point of production within the cerebral ventricles to its point of absorption into the systemic circulation. "The molecular mechanism was reported to be Rnd3 deficiency and consequent enhancement of Notch signaling activity, resulting in the overgrowth of aqueduct ependymal cells and obstructive hydrocephalus." (PMID 35047005, 2021). "RND3 deficiency promotes mouse ependymal epithelia proliferation, which in turn results in aqueduct stenosis and hydrocephalus development." (PMID 26108681, 2015). "Deletion of the Rnd3 gene results in severe obstructive hydrocephalus with enlargements of the lateral and third ventricles, but normal fourth ventricle size, indicating the blocking of the cerebral aqueduct." (PMID 35047005, 2021). "For example, Rnd3 interacts preferentially with plexin‐B2 of the three plexin‐B proteins to induce cell rounding, whereas Rnd3 regulates Notch signalling in the ependymal epithelium, resulting in hydrocephalus through epithelial overgrowth in RND3 null mice." (PMID 31332862, 2019). "Hydrocephalus could result from aqueductal stenosis induced through genetic deletion of Rho family guanosine triphosphatase 3 (Rnd3) and regulating the Notch signaling activity." (PMID 35047005, 2021).
Insulin resistance (3 papers, 2019 to 2021). Increased resistance towards insulin, that is, diminished effectiveness of insulin in reducing blood glucose levels. "Rho family GTPase 3 (RND3), PARD6A, TLE2, FBLN2, COL4A1, and COL4A2 are novel biomarkers for the development of insulin resistance." (PMID 30678306, 2019).
atherosclerosis (2 papers, 2020 to 2023). A disease characterized by the build-up of fatty material and calcium deposition in the arterial wall resulting in partial or complete occlusion of the arterial lumen. "Having demonstrated the protective role of EC‐Rnd3 on atherosclerosis and the underlying mechanism, endothelial‐specific Rnd3 knockout mice (Rnd3ECKO) were generated and crossed with ApoeKO mice to produce ApoeKORnd3ECKO mice." (PMID 37743632, 2023). "Of the remaining ten suggestive hits, two contain biologically plausible genes: rs55895454 (cytoband 2q23.3) is best associated with baPWV (β = 0.065, p = 9.97x10-8) and is close to RND3 (14 kb), a gene associated with atherosclerosis." (PMID 32790701, 2020). "In our hands, Rnd3 deficiency reduced TRAF6 degradation, increased TRAF6 protein levels, and exacerbated endothelial pyroptosis and atherosclerosis by reducing K48‐linked ubiquitination of TRAF6." (PMID 37743632, 2023). "Of note, Rnd3 seems to exhibit profound interaction in ECs directly through Rock1 or NF‐κB in atherosclerosis." (PMID 37743632, 2023). "Downregulation of Rnd3 sensitized ECs to pyroptosis under oxidized low density lipoprotein (oxLDL) challenge and exacerbated atherosclerosis, while overexpression of Rnd3 effectively prevented these effects." (PMID 37743632, 2023). "Our results noted downregulated Rnd3 expression with increased endothelial pyroptosis during atherosclerosis progression." (PMID 37743632, 2023). "It was indicated that endothelial cell knockdown of TRAF6 may suppress atherosclerosis itself, in addition to counteracting atherosclerosis aggravated by Rnd3 knockdown." (PMID 37743632, 2023). "Next, we reported a protective effect of EC Rnd3 in atherosclerosis using two animal models." (PMID 37743632, 2023). "To evaluate whether endothelial Rnd3 is involved in the pathological progression of atherosclerosis, we performed immunofluorescence staining at the aortic roots of wild type (WT) and ApoeKO mice, following high‐fat diet (HFD) feeding for 8 weeks." (PMID 37743632, 2023). "In conclusion, findings from our current study have provided the first evidence that Rnd3 regulates pyroptosis of ECs and identifies a new mechanism by which Rnd3 regulates inflammatory signaling, thus providing therapeutic potential for targeting Rnd3 in the treatment of atherosclerosis." (PMID 37743632, 2023). "Furthermore, Rnd3 has been found to suppress inflammation after myocardial infarction, offering a promising strategy for mitigating chronic inflammation in the progression of atherosclerosis." (PMID 37743632, 2023). "As expected, Oil Red O staining showed that TRAF6 knockdown mitigated 52.6 ± 3.8% of plaque area formation in ApoeKORnd3ECKO mice, suggesting a signal interaction between Rnd3 and TRAF6 in ECs during atherosclerosis." (PMID 37743632, 2023). "However, the role of Rnd3 in atherosclerosis has not been adequately investigated, making it essential to establish a theoretical foundation for its involvement." (PMID 37743632, 2023).
bladder cancer (2 papers, 2018 to 2024). "Immunohistochemistry (IHC) and Western Blot (WB) analyses were used to assess the expression levels of SIRT7/EZH2 and RND3 in bladder cancer tissues, normal ureteral epithelial cells, and bladder cancer cell lines." (PMID 39719443, 2024). "As exemplified by the LATS2 and RND3 genes, vitamin C restored 5hmC levels in T24 cells; these levels were relatively low in bladder cancer cells compared with normal bladder cells, and 5mC showed an opposite trend." (PMID 30005692, 2018). "Overall, in the promoter region of the RND3 gene, SIRT7 upregulated H3K27me3 and EZH2 downregulated H3K18ac, leading to a decline in RND3 expression and CDDP sensitivity in bladder cancer cells." (PMID 39719443, 2024).
cardiomyopathy (2 papers, 2014 to 2021). A disease of the heart muscle or myocardium proper. "Compared to wild-type ones, Rnd3+/− mice displayed apoptotic cardiomyopathy when exposed to pressure overload." (PMID 34306321, 2021). "Further evidence has revealed that insufficient Rnd3 results in apoptotic cardiomyopathy with heart failure." (PMID 34306321, 2021). "Rnd3, a member of the Rnd family, has been proved as a key factor in the pathophysiology process of cardiomyopathy, heart failure, and cancer." (PMID 34306321, 2021).